RNF213 (ring finger protein 213)
Diseases named in the same sentence as RNF213 in open-access papers (continued):
Sharing a sentence is not in itself a finding about the gene and the disease.
Hypertension (14 papers, 2016 to 2025). The presence of chronic increased pressure in the systemic arterial system. "Hypertension has been verified to be a strong risk factor for ICAS development in case of RNF213 mutations, including Arg4810Lys." (PMID 40869185, 2025). "In participants with sodium intake ≥2 g/day, C6orf10-HLA-DQB1 rs6913309, and RNF213 rs112735431 were associated with increased risk of hypertension." (PMID 32854392, 2020). "Further studies to find association between the rs112735431 polymorphism in RNF213 and hypertension in other races/ethnicities are also needed." (PMID 32854392, 2020). "The present study was designed to investigate the association of MTHFR (rs1801133, rs1801131, rs9651118), TCN2 (rs117353193) and RNF213 (rs9916351) gene variants with the susceptibility of hypertension and BP among the population of northeast in China." (PMID 31815282, 2019). "The present study was conducted to examine the association of MTHFR rs1801133, rs1801131, rs9651118, TCN2 rs117353193 and RNF213 rs9916351 gene polymorphisms with the risk of hypertension and BP in Northeast Chinese population." (PMID 31815282, 2019). "In this study, all 6 ICASO patients with RNF213 p.R4810K variant had hypertension and 4 patients had diabetes." (PMID 29165136, 2017). "TCN2 rs117353193 might serve as a protective factor in hypertension, and RNF213 rs9916351 might be a risk factor that is linked to increase BP level in Northeast Chinese population." (PMID 31815282, 2019). "In summary, our study suggests that the TCN2 rs117353193 gene polymorphism might serve as protective factor in hypertension, and the RNF213 rs9916351 gene polymorphism might be an important risk factor that is linked to increase the level of BP among the population of northeast in China." (PMID 31815282, 2019). "An analysis of patients with intracranial cervicocerebral artery dissections (IC-CADs) showed that RNF213 Arg4810Lys was more common in patients than controls and was independently associated with IC-CAD apart from hypertension." (PMID 40869185, 2025). "Methylenetetrahydrofolate reductase gene (MTHFR), transcobalaminII (TCN2) and ring finger protein 213 (RNF213) are related to homocysteine (Hcy) level and are of great significance for hypertension." (PMID 31815282, 2019). "We aimed to evaluate the associations of MTHFR (rs1801133, rs1801131, rs9651118), TCN2 (rs117353193) and RNF213 (rs9916351) with hypertension and blood pressure (BP)." (PMID 31815282, 2019). "The RNF213 p.R4810K variant has been identified not only in MMD cases worldwide but also in association with other cardiovascular diseases and vascular risk factors, including ischemic stroke and hypertension." (PMID 40225941, 2024). "Rare variants in RNF213 have also been found in European MMA patients with incomplete penetrance and are today a recognized susceptibility factor for other cardiovascular disorders, from extracerebral artery stenosis to hypertension." (PMID 36012218, 2022). "We may assume that excess sodium intake could be a provoking factor for the genetic effect of RNF213 on hypertension." (PMID 32854392, 2020). "Regarding RNF213, it has been proved to be a susceptible gene to MMD, but it has also been reported to be involved in other vascular disorders such as coronary heart disease, hypertension, aneurysm and heterogeneous intracerebral vasculopathy." (PMID 31815282, 2019). "MTHFR rs9651118, TCN2 rs117353193 and RNF213 rs9916351 were recently revealed as the novel susceptibility loci for MMD by a genome-wide association study, no studies were conducted concerning the link to hypertension, and more evidences are needed to support our results." (PMID 31815282, 2019).
ischemic stroke (14 papers, 2016 to 2025). A stroke disorder caused by obstruction of blood flow to the brain, due to thrombotic (local blood clot formation) or embolic (due to a blood clot or other material traveling from another site) event. "Our results are consistent with the result of a recent study demonstrating that the RNF213 p.R4810K mutation is common in early-onset ischemic stroke with M1 or A1 stenosis." (PMID 39191959, 2025). "Intracranial artery stenosis (ICAS) is a significant contributor to ischemic stroke, with the RNF213 p.Arg4810Lys variant identified as a related genetic factor." (PMID 39531151, 2025). "The presence of RNF213 4810G > A variant was at increased risk for ischemic stroke, which was largely attributable to large-artery atherosclerosis." (PMID 32182997, 2020). "Additionally, there is also a significant association of the RNF213 variant with ischemic stroke especially with cervical/intracranial large artery atherosclerosis." (PMID 34736485, 2021). "Although the RNF213 variant group is more likely to develop stenosis of large arteries, it may be speculated that compensatory mechanisms, such as the development of collateral blood flow, play a role in mitigating the risk of ischemic stroke." (PMID 39531151, 2025). "By bridging human population genetic studies with basic science research, this review provides a comprehensive perspective on RNF213’s significance in ischemic stroke and MMD and outlines critical areas for future research." (PMID 39857601, 2024). "Initially identified as the primary susceptibility gene for MMD, RNF213—notably the p.R4810K variant—has been strongly linked to intracranial artery stenosis (ICAS) and various ischemic stroke subtypes, particularly in East Asian populations." (PMID 39857601, 2024). "This narrative review explores the current understandings of RNF213’s multifaceted role in ischemic stroke and MMD." (PMID 39857601, 2024). "Additional studies in healthy carriers or other ischemic stroke and TIA cohorts are required to determine precisely when the RNF213 p.R4810K variant leads to the observed arterial variations." (PMID 34335228, 2021). "RNF213 has also been reported to be a susceptibility gene for non-cardioembolic stroke and ischemic stroke attributable to large artery atherosclerosis." (PMID 39857601, 2024). "RNF213 p.R4810K variant carriers have smaller cervical arterial outer diameters in both anterior and posterior circulations than noncarriers with ischemic stroke." (PMID 41582976, 2022). "Therefore, this study aimed to examine the association between the RNF213 p.Arg4810Lys variant and long-term clinical outcomes in patients with asymptomatic ICAS, focusing on the progression of ipsilateral ischemic stroke and stenosis during the follow-up period." (PMID 39531151, 2025). "Furthermore, this nonsynonymous p.R4810K variant accounts for up to 25% of sporadic ischemic stroke with ICA stenosis in East Asia, even without meeting the diagnostic criteria of MMD, which has led to a novel disease concept of RNF213-related vasculopathy." (PMID 33482763, 2021).
atherosclerosis (13 papers, 2016 to 2025). A disease characterized by the build-up of fatty material and calcium deposition in the arterial wall resulting in partial or complete occlusion of the arterial lumen. "The RNF213 variant is a risk factor for various vascular diseases, including vascular occlusive disease and atherosclerosis." (PMID 40485582, 2025). "The RNF213 p.R4810K mutation is considered a risk factor for anterior circulation stenosis, especially in younger patients with a lower burden of atherosclerosis." (PMID 39191959, 2025). "In previous Japanese and Korean studies, a particular subset of ICASO mainly diagnosed as atherosclerosis, associated with RNF213 p.R4810K variant (odds ratios, 16.8 and 22.3; 95% confidence intervals, 3.81–74.5 and 3.0–164.1; both p < 0.0001 for Japanese and Korean, respectively)." (PMID 29165136, 2017). "Further functional studies are needed to clarify how RNF213 affects the risk of vascular disease including CAD and to illuminate the differences between RNF213-related vascular disorders and atherosclerosis." (PMID 28414759, 2017). "We prefer to agree that there exist a new entity of ICASO caused by the RNF213 p.R4810K variant, which can be differentiated from ICASO caused by atherosclerosis by using genetic analysis." (PMID 29165161, 2017). "Both atherosclerosis and autoimmune diseases are driven by inflammatory processes, and research has shown that proinflammatory cytokines such as tumor necrosis factor-alpha (TNFα) and interferon-gamma (IFNγ) can synergistically induce RNF213 expression, leading to angiogenesis in vitro and in vivo." (PMID 39857601, 2024).
coronary artery disease (11 papers, 2017 to 2025). "Single and multiple regression analyses revealed that the max-IMT in the validation group was significantly associated with age, sex, RNF213 p.Arg4810Lys, and a history of coronary artery disease." (PMID 39958261, 2025). "The RNF213 p.R4810K variant appears to be significantly associated with coronary artery disease in the Japanese population." (PMID 28414759, 2017). "We genotyped the RNF213 p.R4810K variant in 956 coronary artery disease patients and 716 controls and tested the association between p.R4810K and coronary artery disease." (PMID 28414759, 2017). "Other heterozygous RNF213 mutations have also been observed in some vascular diseases, such as intracranial artery aneurysm and dissection, thoracic aortic aneurysm and dissection, and coronary artery disease." (PMID 39857601, 2024). "Coronary artery disease has been attributed to the RNF213 p.R4810K variant." (PMID 38115307, 2023). "Notably, results of a previous study demonstrated that the RNF213 p.R4810K variant was significantly associated with coronary artery disease." (PMID 34753383, 2021). "Furthermore, other studies recently showed that RNF213 p.Arg4810Lys is associated with coronary artery disease and pulmonary hypertension." (PMID 32686731, 2020). "Furthermore, RNF213 p.Arg4810Lys was associated with coronary artery disease and pulmonary hypertension." (PMID 32686731, 2020). "In multiple regression analysis, max-IMT was associated with age (β = 0.348, P < 0.0001), sex (β = 0.179, P < 0.0001), RNF213 p.Arg4810Lys (β = 0.179, P < 0.0001), history of coronary artery disease (β = 0.124, P = 0.007), and smoking (β = 0.127, P = 0.011)." (PMID 39958261, 2025). "RNF213 Arg4810Lys has also been linked with coronary artery disease (CAD) in Japanese patients." (PMID 40869185, 2025). "RNF213 Arg4810Lys is increasingly recognized for its implications in coronary artery disease (CAD) and related cardiovascular conditions." (PMID 40869185, 2025). "While prior research has acknowledged the concurrence of significant coronary artery disease in MMD, no current insights exist on the evaluation of coronary artery disease in individuals with the RNF213 p.R4810K variant but without MMD." (PMID 38115307, 2023). "Both mutations in RNF213 and GUCY1A3 cause not only MMD, but also non-moyamoya intracranial arterial diseases, coronary artery disease, and pulmonary artery hypertension." (PMID 34381413, 2021).
intracranial aneurysms (11 papers, 2017 to 2025). "A recent study demonstrated the association of RNF213 with intracranial aneurysms in French-Canadian patients, which are characterized by thin tunica media and internal elastic lamina in contrast to MMD and other intracranial artery stenotic diseases." (PMID 32686731, 2020). "Additionally, the RNF213 variants, such as p.Arg2438Cys and p.Ala2826Thr, have been identified in French-Canadian patients with intracranial aneurysms." (PMID 40869930, 2025). "Whole-exome sequencing of 233 French–Canadian patients with intracranial aneurysms identified 17 deleterious rare RNF213 variants, and the RNF213 single-nucleotide polymorphism rs6565666 was significantly associated with the occurrence of intracranial aneurysms in the French–Canadian population." (PMID 35455046, 2022). "However, two variants of RNF213 (p.Arg2438Cys and p.Ala2826Thr) were found in intracranial aneurysm patients in a French-Canadian population." (PMID 29160859, 2017). "However, limited studies have investigated the relationship between RNF213 and intracranial aneurysms, leaving various aspects, including the site, morphology (saccular, fusiform, or dissected), and clinical characteristics of these aneurysms, unclear." (PMID 40869930, 2025). "Beyond conflicting reports regarding the functional role of RNF213, epidemiologic data have shown significant associations between RNF213 variants and intracranial vascular disorders including MMD, ICASO, cerebral artery dissection, and intracranial aneurysm." (PMID 32182997, 2020).
diabetes (9 papers, 2015 to 2025). "Namely, in Akita mice (which develop diabetes spontaneously) the knockout of RNF213 lowers glucose tolerance by 20% and leads to increased insulin contents in pancreases (by 150%) compared to wild type animals." (PMID 33472578, 2021). "The authors tested whether RNF213 ablation (KO) influenced the development of diabetes and intracranial arteries around the circle of Willis." (PMID 26662949, 2016). "Additionally, we identified several genes with cASE that have been associated with diabetes (GIPC1, USP36, RNF213, KCTD12) or obesity (PIP5K1A) (78, 79, 81, –, 83)." (PMID 27709125, 2016). "Patients with the RNF213 variant were younger, while female gender and diabetes was more prevalent in patients without this variant." (PMID 26125557, 2015). "The presence of basal collaterals, bilateral involvement on angiography, and absence of diabetes were independently associated with the presence of the RNF213 variant." (PMID 26125557, 2015). "For instance, in pathological conditions such as diabetes, ischemia, or inflammation, disruptions in cellular metabolism could impair the activity of RNF213 and its ability to regulate Cav-1, leading to endothelial dysfunction and promoting vascular abnormalities." (PMID 40497951, 2025).
pulmonary hypertension (8 papers, 2021 to 2025). Increased pressure within the pulmonary circulation due to lung or heart disorder. "The RNF213 Arg4810Lys mutation significantly contributes to a range of vasculopathies, including intracranial artery stenosis, extracranial stenosis, and pulmonary hypertension, as well as coronary and renal artery diseases." (PMID 40869185, 2025). "Inflammation was reported as a recurrent pathological feature observed in patients with the RNF213 Arg4810Lys mutation and pulmonary hypertension." (PMID 40869185, 2025). "In particular, the RNF213 p.Arg4810Lys variant was associated with adverse clinical outcomes in pulmonary arterial hypertension, potentially necessitating earlier consideration of lung transplantation for carriers of this variant." (PMID 39531151, 2025). "Recent reports have linked the RNF213 p.Arg4810Lys variant to coronary artery stenosis, pulmonary artery stenosis, pulmonary arterial hypertension, and renal artery stenosis." (PMID 39531151, 2025). "Hence, these findings suggest the potential for patients with RNF213-associated vascular disease primarily affecting pulmonary capillary levels to be diagnosed with pulmonary arterial hypertension." (PMID 39803001, 2024). "Transgenic mice with a vascular endothelial cell-specific RNF213 mutation, corresponding to the human p.Arg4810Lys variant, developed pulmonary hypertension after exposure to hypoxia, suggesting that environmental factors may trigger vasculopathy among susceptible individuals." (PMID 35455046, 2022). "The right ventricular outflow tract acceleration time (RVOT-ACT), which is evaluated with echocardiography, is initially prolonged in the asymptomatic phase of RNF213 p.R4810K-related pulmonary hypertension in our previous study." (PMID 41009011, 2025). "RNF213, a susceptibility gene for MMD, has also been recently implicated in extracranial vascular diseases, such as pulmonary hypertension (PH)." (PMID 40869987, 2025). "The study concludes that longer RVOT-ACT in variant carriers may reflect expansion of the pulmonary vascular bed due to abnormal collateral networks and capillary dilation in the early, preclinical stage of RNF213-related pulmonary hypertension." (PMID 40869987, 2025). "Although RNF213 p.R4810K is most commonly associated with MMD, this variant has also been linked to other vascular diseases, such as ICAS, peripheral pulmonary artery stenosis, and pulmonary arterial hypertension." (PMID 39857601, 2024).
breast carcinoma (7 papers, 2018 to 2025). "Previous studies have shown that RNF213 co-mutates with NF1 in human breast cancer samples." (PMID 39338204, 2024). "In breast cancer, RNF213 is differentially expressed in primary tumors and is correlated with overall survival in patients with basal-like sub-type breast cancer." (PMID 39869563, 2025). "The function of RNF213 in cancer remains poorly understood; however, a possible role in the hypoxia-sensitivity of breast cancer cells has recently been reported." (PMID 37446001, 2023). "In breast cancer cells, RNF213-dependent ubiquitylation involved multiple proteins involved in ubiquitin metabolism, including E1s, E2s, E3s, and deubiquitylases." (PMID 35135845, 2022). "In adipocyte, PTP1B mediated higher expression of RNF213 by TNF-α, while PTP1B suppresses E3 ligase activity of RNF213 in a breast cancer cell line under hypoxic condition." (PMID 34381413, 2021). "RNF213 globally affects the ubiquitylome of HER2+ breast cancer cells and HeLa Flp-In T-Rex cells." (PMID 35135845, 2022). "RNF213 contains AAA-ATPase and RING E3 ligase domains in the same molecule, is associated with MMD, and is required for the toxic effects of PTP1B deficiency/inhibition in hypoxic HER2+ breast cancer cells." (PMID 35135845, 2022). "However, ERBB2 amplification was often observed as arm-level events or separate from pter-located GISTIC peaks, including ASPSCR1 and RNF213, which is in stark contrast to the minimal amplification of ERBB2 observed in human breast cancers (inlet)." (PMID 32680987, 2020).
Down syndrome (7 papers, 2016 to 2025). "For example, Down syndrome patients carrying this mutation face higher risks of vascular dysfunction and complications, indicating that RNF213 could act as a disease modifier in these contexts." (PMID 40869185, 2025). "The RNF213 gene may interact with the genes on chromosome 21 that influence vascular physiology and elasticity in patients with Down syndrome, resulting in the whole picture of moyamoya syndrome." (PMID 35494994, 2022). "Nevertheless, an interaction between RNF213 and genes on chromosome 21 may result in moyamoya syndrome in persons with Down syndrome." (PMID 35494994, 2022). "The RNF213 gene may interact with the genes on chromosome 21 that influence vascular physiology and elasticity in patients with Down syndrome, resulting in the picture of moyamoya syndrome." (PMID 35494994, 2022). "In Down syndrome, the high prevalence of MMS suggests potential interactions between the RNF213 gene and the genes on chromosome 21 regulating vascular physiology and elasticity in these patients." (PMID 40508049, 2025). "Notably, specific modifier genes have been identified in different genetic contexts: RNF213, MRVI1, BMPR2, and ABCC8 in neurofibromatosis type 1, and RNF213, MRVI1, and NF1 in Down syndrome." (PMID 40508049, 2025).